CD4 (CD4 molecule)
Diseases named in the same sentence as CD4 in open-access papers (continued):
Sharing a sentence is not in itself a finding about the gene and the disease.
Hypertension (continued). "Male sex, hypertension, metabolic factors, older age, alcohol/drug abuse, HIV RNA, high viral load, and CD4 count < 200 cells/μL have more strongly predicted ischemic stroke." (PMID 37770849, 2023). "Inversely correlated with KTD were higher body weight, higher eGFR, higher current CD4 cell count, older age, history of AIDS, hypertension, and longer time from HIV-1 infection diagnosis." (PMID 37872903, 2023). "The changes in naïve and memory T lymphocyte population, CD4/CD8, and CMV seropositivity included in IRP are important markers of health status in the elderly that are dependent on hypertension." (PMID 35053985, 2022). "The unconventional and rather small subgroup of γδ T cells has receptors composed of γ- and δ-chains and plays a role in hypertension by producing IL-17A and IFN-γ (for further elaboration of the hypertensive effects of IL-17A and IFN-y, see CD4+ T cells)." (PMID 35354938, 2022). "The 61% elderly individuals with hypertension demonstrated the CD4/CD8 ratio within the reference range (≥1 or ≤2.5) and only 4% had a CD4/CD8 ratio of <1." (PMID 35053985, 2022). "A potential mechanism by which CD4+ cells contribute to hypertension is that these cells secrete inflammatory cytokines IFNγ and Interleukin-17 (IL-17), as mice deficient in these cytokines failed to secrete these cytokines and develop hypertension in response to ANG II infusion." (PMID 36160839, 2022). "As proven elsewhere, more advanced HIV disease (WHO stage III/IV, low CD4, and low Hb) is protective against prevalent HTN while low BMI (<18 kg/m2) is protective against incident hypertension." (PMID 34292956, 2021). "Sex-specific changes in the number of CD4 memory T cells (males > females) and M2-like macrophages (females > males) in PVATs occur with a HFD before hypertension developed." (PMID 33815135, 2021). "In this experiment, the transfer of Th17 cells enhances the proportion of CD4+IL-17A+ (Th17) cells in the PBMCs and the spleen of recipient SHR by which hypertension consequently develops." (PMID 33688497, 2021). "The prevalence of an inverted CD4/CD8 ratio increasing with age and the presence of metabolic disorders such as DM2, hypertension, overweight, and kidney and heart diseases." (PMID 34683357, 2021). "T-cell-derived cytokines, such as IFNγ and TNFα (from CD8+ and CD4+ TH1) and IL-17 (from γδT cell and CD4+ TH17), mediate endothelial dysfunction and cardiac, renal, and neural damage, aggravating hypertension." (PMID 34680058, 2021). "These multivariable models were adjusted for the following variables: current tobacco smoker, hypertension, microalbuminuria, Centers for Diseases Control (CDC) stage C, 2008 eGFR, CD4+ T-cell nadir, and the current CD4+ T-cell count." (PMID 31980868, 2020). "This doctoral research presents data on quality of care in the ICDM model as well as the effectiveness of the model in controlling CD4 counts and blood pressure of HIV and hypertension patients, respectively." (PMID 32316885, 2020). "Recently, we have shown that the percentage of both CD4+TNF+ and CD8+TNF+ T cells in perivascular adipose tissue was higher in Ang II–dependent hypertension in comparison with control animals." (PMID 31321561, 2019). "CD4 T cell count < 50 cells/μL and increased duration of ART were independent predictors of sustained hypertension throughout the study period." (PMID 31165257, 2019). "Simple logistic regressions evaluating HIV-status, WHO stage, CD4 count, and ART as predictors of hypertension." (PMID 30596667, 2018). "We have here provided evidence that CD4+CD25+ T cells are markedly diminished in the peripheral blood of SHRs, suggesting that lower Tregs prevail in hypertension-mediated inflammation." (PMID 30151015, 2018). "More recently, it has been found that Tregs (CD4+CD25+FoxP3+) can act to limit Ang II–induced inflammation and damage in the vasculature and heart, thereby reducing the extent of hypertension and cardiac remodeling." (PMID 29688896, 2018).
Hypertension (continued). "The inhibition of CD4+ and CD8+ Teff infiltration was accompanied by a marked blunting of Ang II–induced hypertension, interstitial fibrosis, and cardiomyocyte hypertrophy." (PMID 29688896, 2018). "Previous studies demonstrated that as the subset of CD4+ helper (Th) cells, Th1 and Th17 and their cytokine secretion profile IFN-γ and IL-17 were critical in the angiotensin II-induced hypertension model." (PMID 29358851, 2017). "HIV-positive women were older, had lower CD4 cell count and HDL cholesterol levels, and were more likely to take medications for hypertension compared to HIV-negative women." (PMID 29206233, 2017). "The prevalence of hypertension was lowest in the group with the lowest average CD4+ T-cell count (HIV-infected ART-naive) and highest in the group in which the CD4+ T-cell count had been low and had then been reconstituted in the setting of ART." (PMID 25070128, 2014). "The network in the MCA with largest number of up-regulated focus genes affected by hypertension plus hypercholesterolemia showed many molecules related to ERK 1/2, interferon alpha, IL12, SYK, CD2, CD4, and CD244." (PMID 23874591, 2013). "Compared with the patients on zidovudine patients on stavudine were more frequently male, had more often a family history of hypertension, had been on ART for a shorter time, and had a higher median CD4 count at enrollment." (PMID 24052885, 2012). "Hypertension-specific antigens can be phagocytosed and presented by dendritic cells (DCs) to B cells and T cells, thereby promoting the differentiation of plasma cells and effector T cell subsets (CD8+ T cells, CD4+ T cells, and regulatory T cells)." (PMID 40606611, 2025). "Several risk factors have been identified for the development of T2DM in older PLWH, including the duration of HIV infection, lower CD4+ T cell nadir, long durations of HIV infection, use of older-generation antiretroviral therapy, high BMI, and arterial hypertension." (PMID 40150513, 2025). "Our study found an increased percentage of CD8+ T cells and a decreased percentage of CD4+ T cells during the acute phase of stroke in patients with a history of hypertension (HT), compared to those without HT." (PMID 40342517, 2025). "Among them, the independent variables with non-zero coefficient estimates are the selected independent variables, including age, Coinfection, CD4+, CD4+/CD8+ ratio, multiple lung infiltrates, smoking, hypertension, ICU admission days, and hospital admission days." (PMID 38811907, 2024). "There were statistically significant differences in age, smoking, hypertension, CCI, ICU admission days, hospital admission days, CD4+, CD8+, CD4+/CD8+, lymphocyte count, multiple lung lobe infiltrations, and bacterial coinfection, MuLBSTA between severe and non-severe groups of viral pneumonia." (PMID 38811907, 2024). "IL-17A–producing CD4+ T cells and γδ T cells are an important source of inflammation in hypertension and recognize IsoLG-adducted peptides in mouse models of nonischemic heart failure." (PMID 39145457, 2024). "However, only a small number of pathways were enriched in CD4 TEM cells, which suggests that these cells underwent relatively few functional changes in hypertension." (PMID 37009484, 2023). "In addition, some studies indicate that CD4+ T lymphopenia was prevalent in patients with SARS-CoV-2 infection and hypertension." (PMID 36839596, 2023). "Concerning atherogenic indexes like TC/HDL-C, log (TG/HDL-C), LDL-C/HDL-C, and non-HDL-C/HDL-C, increased age, complicated with hypertension, decreased CD4/CD8 ratio and HIV-1 RNA more than 105 copies/mL were common risk factors." (PMID 37705002, 2023). "In CD4+ and CD8+ T cells, IFNγ secretion was higher in SARS-CoV-2 patients with hypertension." (PMID 36839596, 2023).
Hypertension (continued). "In another animal model, the treatment of obstructive-sleep-apnea-induced hypertension in rats with the probiotic Lactobacillus rhamnosus GG strain provided a lower level of TMAO and CD4+ T cell induced-type I inflammation, leading to a reduction in hypertension." (PMID 36830968, 2023). "Total CD4+ T cells and total CD8+ T cells have been reported to be reduced in hypertension." (PMID 36891527, 2023). "Statistical results did not change substantively after adjusting for nadir CD4+ T-cell count and hypertension." (PMID 37376619, 2023). "HIV factors of low CD4 count and high viral load, which lead to poorer outcomes, were not related to the burden of hypertension." (PMID 37908015, 2023). "Both CGC+ CD4+ T cells (ρ=0.23, p=0.01) and CGC+ CD8+ T cells (ρ=0.27, p=0.003) were correlated with hemoglobin A1C in a partial Spearman’s correlation analysis adjusted for age, sex, body mass index (BMI), hypertension, statin use, and smoking status (top)." (PMID 36865544, 2023). "The extent of the role of either CD4+ or CD8+ T cells in the progression of hypertension and cardiovascular disease is not yet clear." (PMID 36970367, 2023). "In this context, our focus is on the evidence supporting the notion that metabolic modulators, aimed at improving the impaired CD4+ T cell metabolism in SLE, could serve as a therapeutic alternative in managing hypertension in SLE patients." (PMID 38137363, 2023). "HIV-related factors include viral load, CD4, WHO stages one through four, opportunistic infections including TB and Pneumocystis carinii pneumonia, as well as concomitant conditions such as diabetes, cancer, and high blood pressure." (PMID 37872903, 2023). "Likewise, in a very small study critically ill patients with hypertension who died exhibited prolonged low peripheral blood counts of SARS-CoV-2-S-reactive CD8+ and CD4+ T cells." (PMID 35995830, 2022). "Neither hypertension, left ventricular hypertrophy nor cardiac CD4+ T cells were affected but left ventricular fibrosis was significantly reduced." (PMID 36483558, 2022). "Our analyses revealed that the percentage of CD4+ in men with hypertension was at a similar level as in women without hypertension." (PMID 35053985, 2022). "Baseline CD4 predicted incident hypertension in females and not in males on univariate analysis but did not remain a significant predictor of hypertension on multivariate analysis." (PMID 36465432, 2022). "Mice lacking CD8+ T cells were found to be protected from hypertension, while mice lacking CD4+ cells showed an even increased blood pressure response." (PMID 33394136, 2021). "Despite the absence of an increase in the proportion of CD4+FoxP3+ (Treg) cells in the recipient WKY, the increased proportion of CD4+IL-17A+ (Th17) cells did not affect the onset of hypertension." (PMID 33688497, 2021). "We did not observe differences in the odds of hypertension by CD4 count, viral load or ART among HIV positive individuals in this sample." (PMID 33598392, 2021). "CD4 T cells are critical in driving hypertension among HIV negative individuals and there is indirect evidence from early studies that T lymphocytes in target organs drive inflammation and hypertension." (PMID 33598392, 2021). "ART patients with hypertension were more likely to have higher CD4-cell counts compared to ART patients without hypertension in the whole group analysis." (PMID 34155234, 2021). "At the time of hypertension diagnosis or the last encounter for those who did not develop hypertension, median CD4+ cell count and VL were 431 ± 203 cells/mm3 and 1.6 ± 0.7 log10 copies/ml respectively." (PMID 32487185, 2020). "Further analysis that controlled for demographics and nadir CD4 levels showed that HIV duration (HR 0.90, 95% CI 0.81, 099, p = 0.038), hepatitis C (HR 4.60, 95% CI 1.40, 14.8, p = 0.012), and hypertension (HR 1.24, 95% CI 1.24, 11.9, p = 0.020) were significant factors of mortality." (PMID 32353062, 2020).
Hypertension (continued). "Consistent with our hypothesis, a recent study involving 61 patients with hypertension showed a significant decrease in peripheral blood CD3, CD4 and CD8 T-cell in hypertensive patients versus healthy controls." (PMID 32631365, 2020). "In T2DM and hypertension patients, CD8, CD3, CD19 and CD4/CD8 correlated with 25(OH) vitamin D3." (PMID 32316365, 2020). "No prior studies have examined the relationship between hypertension and CD4+/CD8+ ratios among PLWH." (PMID 32487185, 2020). "TG (OR 6.440, P = 0.250), CD4 T cell < 200 copies/ml (OR 2.635, P = 0.250), WHR (OR 928.39, P = 0.250), hypertension (0R 2.115, P = 0.335), detectable viraemia ≥20 copies/ml (OR 1.375, P = 0.511) demonstrated high odd ratio for predicting low ABI in the study group." (PMID 31429736, 2019). "Further studies into infection-driven immune activation, as a risk factor for CVD, are warranted, but guidelines for prevention of CVD in HIV-infected individuals are urgently needed and should focus on hypertension reduction and close monitoring for those starting ART at lower CD4+ T-cell counts." (PMID 30629187, 2019). "We have confirmed hypertension as the primary CVD risk factor in the region and demonstrated that consequences of immune activation can be reversed irrespective of CD4+ T-cell count recovery, with early benefits for vasculature." (PMID 30629187, 2019). "Although hypertension was evident in almost a quarter of these ART‐experienced participants, hypertension was not independently associated with ART duration, PI use, current or nadir CD4 cell count." (PMID 30990252, 2019). "In patients with hypertension, 25(OH)D3 and total 25(OH)D negatively correlated with CD8 and CD3 and positively correlated with CD19 and CD4/CD8, a finding which suggests that patients with hypertension might also benefit from 25(OH)D3 dietary supplementation." (PMID 29769621, 2018). "There is no independent relationship between CD4 cell count and hypertension after adjusting for important confounders such as BMI, age, sex, HAART use, and duration of HIV infection." (PMID 29610680, 2018). "Indeed, several studies from hypertensive rat and mouse models showed that both CD4+ and CD8+ T cells are involved in the pathogenesis of hypertension, and CD4+ cells are the main adaptive immune players in hypertension." (PMID 30151015, 2018). "In T2DM and hypertension patients, CD8, CD3, CD19 and CD4/CD8 correlated with 25(OH)D3." (PMID 29769621, 2018). "Excitingly, our results also show that Cx40 and Cx43 expression levels in the membranes of CD4+/CD8+ T cells were significantly increased in EHs; in particular, the expression of Cx43 in T lymphocytes was strongly up-regulated by the hypertension mediated inflammatory response." (PMID 28910394, 2017). "The proportions of CD4+ and CD8+ T cells from EHs and NTs were analyzed by flow cytometry to determine which subtype of T cells contributes to the inflammatory pathogenesis of hypertension." (PMID 28910394, 2017). "Noteworthy, none of the HIV parameters (ART, CD4, or viral load) remained as significant predictors of hypertension." (PMID 25490037, 2014). "The prevalence of hypertension tended to be higher among individuals with higher CD4 counts in the youngest age group, but not in the two older groups." (PMID 21779407, 2011). "The prevalence of hypertension was not significantly higher among women with higher CD4 counts in any of the age categories." (PMID 21779407, 2011). "Furthermore, greater frequencies of CD62L+ CD4+ and CD8+ T cells were seen in severely ill diabetic patients compared to non-severe and non-diabetic patients, and increased CD62L+ CD4+ T cells were also seen in severely ill patients with hypertension." (PMID 36817450, 2023). "Furthermore, subsets of CD4+ T cells in peripheral blood were also detected and compared between participants with and without hypertension." (PMID 36678161, 2023).
Hypertension (continued). "Interestingly, men with hypertension showed a similar number of CD4+ lymphocytes to the percentage recorder in women who had not been diagnosed with hypertension." (PMID 35053985, 2022). "However, 34% of hypertensive individuals had a CD4/CD8 ratio > 2.5 when compared to patients without hypertension, where 28% had CD4/CD8 > 2.5." (PMID 35053985, 2022). "Our research showed that the IgG CMV+ elderly diagnosed with hypertension achieved higher values of CD4+ T cells when compared to the controls, which may indicate that the increase in CD4+ T cells in hypertensive patients is independent of CMV infection." (PMID 35053985, 2022). "A study in Cameroon showed that participants who had CD4 cell counts greater than 350 cells/μL were three times more likely to have hypertension than those with CD4 cells less than 350 cells/μL, but there was no linear relationship between CD4 cell count and hypertension." (PMID 33598392, 2021). "In a cohort of 816 PLWH who started ART in 2005–2008 at GHESKIO, 5.3% had hypertension at the time of ART initiation, and this independently predicted mortality during 10 years of follow-up (HR 2.47 [95% CI 1.10–5.57]), after adjusting for age, sex, CD4 count at ART start." (PMID 34351939, 2021). "This could be the first study in sub-Saharan Africa to evaluate the quality of care in an integrated model of care and assess the effectiveness of the model in improving CD4 count and blood pressure of patients receiving treatment for HIV and hypertension in PHC facilities." (PMID 32316885, 2020). "From the results, CD4+IL-17A+ (Th17) cells isolated from SS rats maintained on 20% fructose solution induced hypertension in recipient SS but not SR rats, whereas CD4+IL-17A+ (Th17) cells isolated from SS rats maintained on tap water did not affect blood pressure in either recipient group." (PMID 32179549, 2020). "Many risk factors could contribute to the higher prevalence of hypertension in such HIV-infected population, including older age, male gender, family history of hypertension, longer duration of HIV infection, low CD4 count, high viral burden, and high body mass index." (PMID 31929895, 2019). "Although the percentages of cells with CD4, CD8, CD3, CD19 and CD56 were within the normal reference range for Chinese patients, serum levels of 25(OH)D3 and 25(OH)D2 were significantly correlated with three or more immune markers in CRVD, CAD, T2DM and hypertension patients." (PMID 29769621, 2018). "This study did not identify any independent relationship between CD4 count and hypertension." (PMID 29610680, 2018). "Overall, our results are consistent with those of prior studies showing a remarkably elevated risk of hypertension among HIV patients and individuals of African ancestry and support universal hypertension screening strategies regardless of baseline CD4 count or ART exposure." (PMID 28273105, 2017). "Neither baseline CD4 count (aHR per 25 cell/mm3 increase: 0.98, 95% CI 0.94–1.02, p = 0.300) nor exposure to ART (aHR: 0.95, 95% CI 0.42–2.13, p = 0.907) were associated with the development of hypertension in our cohort." (PMID 28273105, 2017). "Because we lacked data on current CD4+ T-cell count or HIV-1 viral load, our study was unable to explore covariates that may have been associated with low or high blood pressure in the HIV-infected population." (PMID 26315787, 2015). "Regulatory T cells (Tregs)—CD4+ T cells that express CD4, CD25, and FOXP3—are classically understood to reduce inflammation and play an anti-proliferative role in immune responses; as such, these cells may play a protective role in the kidney during the development of hypertension." (PMID 36970367, 2023). "At the time of hypertension diagnosis or the last encounter (for those who did not develop hypertension), a lower recent CD4+/CD8+ ratio (aHR 0.14, 95% CI: 0.06–0.31, p < 0.001) and a higher recent VL (aHR 1.28, 95% CI: 1.08–1.51, p < 0.01) were also associated with incident hypertension." (PMID 32487185, 2020).